CIITA (class II major histocompatibility complex transactivator)
Description:
Essential for transcriptional activity of the HLA class II promoter; activation is via the proximal promoter. Does not bind DNA. May act in a coactivator-like fashion through protein-protein interactions by contacting factors binding to the proximal MHC class II promoter, to elements of the transcription machinery, or both PubMed:8402893, PubMed:7749984,. Alternatively it may activate HLA class II transcription by modifying proteins that bind to the MHC class II promoter. Also mediates enhanced MHC class I transcription; the promoter element requirements for CIITA-mediated transcription are distinct from those of constitutive MHC class I transcription, and CIITA can functionally replace TAF1 at these genes. Activates CD74 transcription. Exhibits intrinsic GTP-stimulated acetyltransferase activity. Exhibits serine/threonine protein kinase activity: can phosphorylate the TFIID component TAF7, the RAP74 subunit of the general transcription factor TFIIF, histone H2B at 'Ser-37' and other histones (in vitro). Has antiviral activity against Ebola virus and coronaviruses, including SARS-CoV-2. Induces resistance by up-regulation of the p41 isoform of CD74, which blocks cathepsin-mediated cleavage of viral glycoproteins, thereby preventing viral fusion. [Isoform 3]: Exhibits dominant-negative suppression of MHC class II gene expression.
Synonyms: MHC2TA; C2TA; NLRA; CIITAIV; MHC2D1
Tractability: PROTAC: ubiquitination databases record sites on it.
Gene: Protein-coding gene on chromosome 16 (10,866,222 to 10,943,021, forward strand). Ensembl gene ENSG00000179583.
Subcellular location: Nucleus; Nucleus, PML body
Subcellular location (Human Protein Atlas): Nucleoplasm
Pathways (Reactome):
Immune System: Interferon gamma signaling
Gene Ontology:
Molecular function: DNA-binding transcription factor binding; histone deacetylase binding; protein binding; protein serine kinase activity; protein-containing complex binding; RNA polymerase II-specific DNA-binding transcription factor binding; transcription coactivator activity; transcription corepressor activity; DNA binding; ATP binding; protein serine/threonine kinase activity
Biological process: host-mediated suppression of symbiont invasion; negative regulation of collagen biosynthetic process; negative regulation of transcription by RNA polymerase II; positive regulation of MHC class I biosynthetic process; positive regulation of MHC class II biosynthetic process; positive regulation of transcription by RNA polymerase II; response to antibiotic; response to type II interferon; type II interferon-mediated signaling pathway; immune response; negative regulation of DNA-templated transcription; regulation of DNA-templated transcription
Cellular component: nucleoplasm; nucleus; PML body
Genetic constraint (gnomAD): Loss-of-function variants: 72 observed, 120.19 expected, observed/expected ratio (o/e) 0.6, 90% interval 0.49 to 0.73. The upper end of that interval is the gene's LOEUF score, 0.73, which puts it in group 2 of 6, group 1 being the genes least tolerant of losing a copy. Missense variants: 1,617 observed, 1,524.2 expected, observed/expected ratio (o/e) 1.06, 90% interval 1.02 to 1.11. Synonymous variants: 763 observed, 666.66 expected, observed/expected ratio (o/e) 1.14, 90% interval 1.08 to 1.22.
Gene-disease validity (ClinGen):
ClinGen rates the evidence that CIITA causes each of these diseases.
MHC class II deficiency (autosomal recessive): Definitive.
Cancer hallmarks: escaping immune response to cancer (suppresses)
Homologues: Orthologues: chimpanzee CIITA (99% identical), macaque CIITA (93% identical), pig CIITA (78% identical), dog CIITA (78% identical), rabbit CIITA (74% identical), mouse Ciita (70% identical), rat Ciita (70% identical), guinea pig CIITA (69% identical). Paralogues in human: NLRC5 (18% identical), NLRP12 (16% identical), NOD1 (16% identical), NLRP3 (16% identical), NOD2 (15% identical), NLRP6 (15% identical), NLRP4 (14% identical), NLRC3 (14% identical), NLRP9 (14% identical), NLRP2 (14% identical), NLRP7 (13% identical), NLRP1 (13% identical), and 8 more.
Diseases named in the same sentence as CIITA in open-access papers:
CIITA is named in the same sentence as 134 diseases in open-access papers, as found by Europe PMC text mining. Sharing a sentence is not in itself a finding about the gene and the disease. The quoted sentences say what the papers report.
melanoma (26 papers, 2008 to 2025). A malignant, usually aggressive tumor composed of atypical, neoplastic melanocytes. "Similar as MHC II genes, CIITA was also significantly higher after co‐culture in the analyzed melanoma cells." (PMID 41078003, 2025). "DNA methylation also regulates the expression of the gene encoding the class II transactivator (CIITA), and hypomethylating agents can restore cytokine-induced expression class II MHC genes in melanoma cells." (PMID 40307913, 2025). "Combined therapy with hypomethylating agents and an HDAC inhibitor trichostatin A potentiated expression of HLA-DR, CIITA and the class II-associated invariant chain peptide (CLIP) in melanoma cells." (PMID 40307913, 2025). "Accordingly, we next focused on elucidating the contribution of the IFNγ‐CIITA‐MHC II axis on melanoma cell resistance to NKmK." (PMID 41078003, 2025). "As for CIITA, generally, when CIITA is expressed by tumor cells, which is very common in melanoma, it has a strongly anti-apoptotic function, consistent with the worse outcome reported here." (PMID 37106775, 2023). "Direct CD4+ T cell recognition of melanoma cell lines expressing MHC-II naturally or after CIITA transduction has been reported in 2 studies." (PMID 36512410, 2023). "CIITA (Class II transactivator) gene was transduced into B16F1 murine melanoma cell line (B16F1- CIITA) by genetic engineering, and the secreted Exos (CIITA- Exo) expressed high level of MHC-II as well as the tumor antigen TRP2." (PMID 36733388, 2022). "In order to determine the clinical relevance of HLA class II expression, the basal HLA class II and/or CIITA expression of melanoma lesions, as well as the level of immune cell infiltration, was correlated to tumor staging." (PMID 34359808, 2021). "Exosomes derived from a CIITA (Class II transactivator) gene modified B16F1 murine melanoma cell line for use as a vaccine (CIITA-Exo) can express MHC II and tumor antigen TRP2." (PMID 33183286, 2020). "Consistently, IFN-γ upregulates CIITA expression on multiple myeloma and melanoma cells increasing their MHC II expression." (PMID 29780381, 2018). "To assess the significance of MHC class II expression in human melanocytic neoplasia, we mined human melanoma Cancer Genome Atlas data comparing expression of CIITA, HLA-DRA, and HLA-DRB with patient survival." (PMID 28647344, 2017). "Exosomes from class II trans-activator (CIITA)-transduced murine melanoma cells contain a large amount of MHC class II and exhibit greater effects on tumor regression." (PMID 26757900, 2016). "Aberrant expression of MHC class II in melanoma is due to expression of CIITA resulting from activation of the B-cell-specific CIITA promoter III and the IFN-γ-inducible CIITA promoter IV." (PMID 24409178, 2013). "In addition, RT‐qPCR analyses of IFNγ‐exposed melanoma cells revealed upregulated expression of CIITA and several MHC II‐related genes (DR‐A, DQ‐A, DP‐A)." (PMID 41078003, 2025). "Similarly, simvastatin, a widely used HMG‐CoA reductase inhibitor, reduced melanoma resistance by inhibiting CIITA expression through STAT1 modulation." (PMID 41078003, 2025). "Our data suggest that CIITA plays a crucial role in melanoma resistance formation, while MHC II expression may serve as a potential resistance biomarker and therapeutic target." (PMID 41078003, 2025). "However, melanoma cells adapt during co‐culture by upregulating CIITA and MHC II in response to interferon gamma (IFNγ), thereby evading NK‐cell lysis." (PMID 41078003, 2025). "Hence, a study transduced B16-F1 murine melanoma cells with MHC class II transcription activator (CIITA) gene to generate Tu-sEVs enriched in MHC II and tumor antigen TRP2 (CIITA-Tu-sEV)." (PMID 37681880, 2023). "Furthermore, the immunohistochemical staining of the TMA demonstrated a heterogeneous expression pattern of HLA-DO and CIITA proteins in the melanoma lesions." (PMID 34359808, 2021).
melanoma (continued). "In metastatic melanoma, the master regulator of MHC genes, Class II Major Histocompatibility Complex Transactivator (CIITA), was significantly downregulated compared to vertical growth phase melanomas, which was considered to account for the discrepancy between expression level and DNA copy number." (PMID 31212865, 2019). "We therefore performed quantitative ChIP experiments to determine whether binding of CIITA to the new targets is induced by IFNγ in a melanoma cell line exhibiting well documented IFNγ induced CIITA expression." (PMID 18437201, 2008). "Our current study enhances the understanding of melanoma cell resistance to NK‐cell cytotoxicity by demonstrating that resistance to NKmK is induced by IFNγ‐mediated interactions between melanoma and NK‐cells, with IFNγ, CIITA, and MHC II playing central roles." (PMID 41078003, 2025). "Aberrant CIITA expression in melanomas results from the activation of both IFNγ-inducible and constitutive CIITA promoters, and deletion of the same AP-1 site that we found differentially occupied by Jun in Fbw7 mutant Hct116 cells compromised CIITA expression in melanoma cells." (PMID 35225231, 2022). "As representatively shown for three selected melanoma cell lines and HaCat as a control, the upregulation of HLA class II mRNA and surface expression by IFN-γ was associated with an increased expression of some HLA class II APM components, e.g., HLA-DO, HLA-DM, CIITA, CLIP and cathepsin S." (PMID 34359808, 2021). "The mechanism of CIITA induction in melanoma is unknown, but MHC class II expression parallels the expression of chemokines CXCL-1 and CXCL-8 and the nuclear expression of NFκB p50 subunit, which are associated with tumor invasiveness and poor prognosis in melanoma." (PMID 24409178, 2013). "In contrast, the mRNA expression of CIITA and MHC-II heavy chain genes was gradually increased from non-responding to partially responding to completely responding melanoma tumors." (PMID 40608411, 2025). "Targeting the master regulator CIITA, which governs MHC II expression and is affected by IFNγ, significantly reduced melanoma cell resistance to NKmK." (PMID 41078003, 2025). "In the human melanoma cell line MelJuSo, BAT3 coordinates the regulation of MHC II via CIITA transactivation, with BAT3 deletion/overexpression inversely correlating with HLA class II levels." (PMID 40362568, 2025). "To confirm this correlation, we analyzed RNA-seq data from seven different melanoma-derived cell lines and found that CIITA transcript levels correlated strongly with HLA-DRA and HLA-DRB levels across this panel of melanoma lines." (PMID 28647344, 2017). "Therefore, the CIITA methylation status of melanoma cells (19/47) was investigated by COBRA analysis, demonstrating a total or partial methylation (25–75%) of the CpG islands in the CIITA promoter." (PMID 34359808, 2021). "Furthermore, in some tumor types, such as multiple myeloma and melanoma cells, IFN-γ can also upregulate the MHC class II transactivator (CIITA) that leads to MHC class II expression." (PMID 29780381, 2018).
bare lymphocyte syndrome (22 papers, 2008 to 2025). "Major histocompatibility complex class II (MHC II) deficiency (bare lymphocyte syndrome type II) is an autosomal-recessive combined immunodeficiency caused by pathogenic variants in the transcriptional regulators CIITA, RFXANK, RFX5, or RFXAP." (PMID 41376631, 2025). "This is the first report of CIITA deficiency in Morocco, and the variant itself is reported here for the first time worldwide, expanding the genetic spectrum of bare lymphocyte syndrome beyond the well-known North African founder mutation in RFXANK." (PMID 41376631, 2025). "In summary, we describe a novel CIITA nonsense mutation (c.1615C>T; p.R539*) causing MHC class II deficiency in two siblings from a consanguineous Moroccan family." (PMID 41376631, 2025). "In humans, genetic mutations of CIITA or other crucial transcription factors for MHCII causes severe immunodeficiency (bare lymphocyte syndrome, BLS)." (PMID 38728204, 2024). "We also measured MHCI mRNA expression by quantitative real-time RT-PCR (qRT-PCR) in in vitro-generated B cell mutants and B cell lines derived from bare lymphocyte syndrome (BLS) patients carrying inactivating mutations in CIITA, RFX5, RFXAP, and RFXANK." (PMID 25811463, 2015). "MHC CIITA was discovered in 1993 as the genetic basis of hereditary major histocompatibility complex Class II deficiency, or bare lymphocyte syndrome (BLS), a disease characterized by severe immunodeficiency due to a lack of MHC Class II expression." (PMID 24137163, 2013). "The role of CIITA in regulating MHC gene transcription is well established: CIITA deficiency or aberrant expression is linked to the Type II bare lymphocyte syndrome and to cancer, respectively." (PMID 24391648, 2013). "On the other hand, CIITA (the class II major histocompatibility complex transactivator) defects are associated with bare lymphocyte syndrome type II, a severe human immunodeficiency syndrome that could modify the inflammation regulation." (PMID 36982971, 2023). "Mutation of CIITA causes Bare Lymphocyte Syndrome, a disease unable to fight against infection." (PMID 23251452, 2012). "Mutations in the CIITA gene were next shown to be one of the causes of the Bare Lymphocyte Syndrome (BLS) (MIM number: 600005), a hereditary immunodeficiency disease characterized by the virtually complete absence of MHC-II expression and a significant reduction in MHC class I (MHC-I) expression." (PMID 18437201, 2008). "Abnormal MHC II expression can lead to immunodeficiency, clinically termed as type II bare lymphocyte syndrome (BLS), which usually results from mutations in the MHC II transactivator (CIITA) and other coactivators." (PMID 35309308, 2022). "As such, it plays a critical role in immune responses: CIITA deficiency results in aberrant MHC gene expression and consequently in autoimmune diseases such as Type II bare lymphocyte syndrome." (PMID 24391648, 2013). "The absence of functional CIITA results in a loss of HLA-II presentation, leading to a hereditary immunodeficiency called type II bare lymphocyte syndrome (BLS) that causes an extreme vulnerability to infections." (PMID 40608405, 2025). "Mutations in CIITA and other MHC-II enhanceosome genes cause the bare lymphocyte syndrome (BLS)." (PMID 39562739, 2024). "Mutations in CIITA in humans are associated with bare lymphocyte syndrome type II, a severe primary immunodeficiency caused by the absence of MHC class II gene expression." (PMID 31697674, 2019). "Not surprisingly, CIITA loss of function mutants are associated with a severe immunodeficiency called bare lymphocyte syndrome (BLS)." (PMID 24319445, 2013). "Apart from CIITA, genes such as RFXANK, RFX5, and RFXAP were also affected in patients with type II BLS." (PMID 35309308, 2022).
lymphoma (16 papers, 2004 to 2025). A malignant (clonal) proliferation of B- lymphocytes or T- lymphocytes which involves the lymph nodes, bone marrow and/or extranodal sites. "For instance, there have been several reports of HLA class II downregulation in lymphoma cells as a consequence of deletions and point mutations of HLA class II genes and their regulators, including CIITA." (PMID 32158444, 2020). "In previous studies, the inactivation of CIITA played a crucial role in lymphomas originating from thymic medullary B cells." (PMID 38145160, 2023). "Next-generation sequencing (NGS) targeting 172 leukemia- and lymphoma-related genes identified ANKRD26-p.Asn267Ser, PTPN11-p.Glu76Lys, CIITA-p.His1119Asn and FAT1-p.Phe765Tyr mutations." (PMID 35912172, 2022). "In lymphomas, an amplification of the PD-L1 gene, or its fusion with the MHC class II transactivator CIITA gene, has resulted in PD-L1 overexpression." (PMID 28635644, 2017). "Recently, defects in MHC class II transactivator (CIITA) synthesis was associated with impaired MHC class II expression in head and neck cancer cells and some lymphomas." (PMID 24782988, 2014). "This is very different from the CIITA-fusions identified in lymphoma, in which the CIITA parts are truncated in the coding region." (PMID 23251452, 2012). "DNA methylation is known to be involved in the regulation of CIITA and MHC gene expression in several tumour cell types, including trophoblast-derived cells, a subset of lymphoma cells, and squamous cell carcinoma." (PMID 14970863, 2004). "Furthermore, our study identifies CIITA, LYZ, MBL2, and CD40 as potential therapeutic targets for various types of lymphoma treatment." (PMID 40360443, 2025). "Abnormal expression of DNMT1 and DNMT3β has been reported in several tumours, including lung, liver, breast, ovarian, colorectal, meningiomas and lymphomas.Reduced expression of CIITA was observed in PBMCs but not in BM." (PMID 26466379, 2015).